TMSB15B (thymosin beta 15B)
Description:
Plays an important role in the organization of the cytoskeleton. Binds to and sequesters actin monomers (G actin) and therefore inhibits actin polymerization (By similarity). May be involved in cell migration.
Synonyms: MGC39900; TMSL8; Tbeta15b
Tractability: No criterion of Open Targets' tractability assessment is met for any kind of drug.
Gene: Protein-coding gene on chromosome X (103,918,896 to 103,966,712, forward strand). Ensembl gene ENSG00000158427.
Subcellular location: Cytoplasm, cytoskeleton
Gene Ontology:
Molecular function: actin monomer binding; protein sequestering activity
Biological process: positive regulation of cell migration; regulation of cell migration; actin filament organization
Cellular component: filamentous actin; cytoskeleton
Homologues: Orthologues: macaque TMSB15B (100% identical). Paralogues in human: TMSB15A (100% identical), TMSB15C (100% identical).
Diseases named in the same sentence as TMSB15B in open-access papers:
TMSB15B is named in the same sentence as 6 diseases in open-access papers, as found by Europe PMC text mining. Sharing a sentence is not in itself a finding about the gene and the disease. The quoted sentences say what the papers report.
breast carcinoma (1 paper, 2019). "Interestingly, AK291479 overlaps with the transcript of thymosin beta-15B (TMSB15B), one of the two isoforms of human thymosin beta 15, TMSB15A and TMSB15B, which show approximately equivalent levels of expression in MCF-7 breast cancer cells." (PMID 31191314, 2019).
prostate carcinoma (1 paper, 2019). A carcinoma that arises from epithelial cells of the prostate gland. "Interestingly, the thymosin beta 15B (TMSB15B) is involved in epidermal growth factor-induced migration of prostate cancer cells." (PMID 30626092, 2019).
tumor (1 paper, 2022). "Furthermore, we found that the expression of TMSB10 in the tumor tissues was the highest among these seven TMSs, and TMSB15A, TMSB4Y and TMSB15B showed relatively low expression." (PMID 36163046, 2022).
TMSB15B also shares sentences with these, for which no sentence is quoted: cancer (1 paper); glioblastoma (1); hypothyroidism (1).